IFNG (interferon gamma)
Diseases named in the same sentence as IFNG in open-access papers (continued):
Sharing a sentence is not in itself a finding about the gene and the disease.
bladder cancer (81 papers, 2004 to 2025). "When assessed in bladder cancers, the interferon gamma signature was associated with a subset of patients who showed significantly better survival." (PMID 36358715, 2022). "Expression of IFNγ inducible molecular signature was associated with good overall response to atezolizumab in bladder cancer patients." (PMID 31779626, 2019). "Our results support a role for FOXA1 as a pioneer factor that regulates chromatin structure, and our findings suggest that global epigenetic reprogramming following FOXA1 loss-of-function contributes to the IFNγ-dominant signature found in the squamous regions of mixed histology bladder cancers." (PMID 36323682, 2022). "It has already been reported that damaging mutations in the IFNγ signaling pathway and antigen presentation pathway are associated with metastasis and higher resistance to the checkpoint blocking therapy with anti-PD-L1/PD-1 in a number of tumor types, including bladder cancer." (PMID 31552026, 2019). "IFNγ can be detected in the urine of bladder cancer patients following intravesical Bacillus Calmette–Guerin therapy." (PMID 38339062, 2024). "In contrast, BCG was totally ineffective in IFNγ or IL-12 knockout mice in a syngeneic orthotopic model of bladder cancer." (PMID 37520557, 2023). "In conclusion, this study suggests a reconsideration of immunotherapy protocols for bladder cancers based on IFNγ-response signature." (PMID 36358715, 2022). "In an orthotopic MB49 mouse bladder cancer model, IFNγ was critical for intrinsic tumour surveillance and an Ifng-knockout rendered BCG ineffective." (PMID 36358715, 2022). "We applied a curated urothelial in vitro IFNγ-response gene set to the unsupervised clustering of bladder cancer cohorts to derive an “IFNγ-signature” score." (PMID 36358715, 2022). "We used the results to generate an IFNγ response signature that we used to study bladder cancer cohorts." (PMID 36358715, 2022). "Fourth, PD-L1 gene expression, as well as IFNγ-signalling expression, correlated positively with hypoxia in bladder cancers in silico." (PMID 34819027, 2021). "First, hypoxia decreased PD-L1 expression and abrogated IFNγ-induced increases in PD-L1 in bladder cancer cells." (PMID 34819027, 2021). "A number of studies have demonstrated the antiproliferative effect of IFNγ on bladder cancer cells, and inhibition of IFNγ leads to increased proliferation and invasion." (PMID 32922441, 2020). "IFNγ is of specific relevance in bladder cancer as it is a major cytokine released by tumor infiltrating lymphocytes thought to be important for anti-tumor responses and has potential for use as a biomarker of outcome in this condition." (PMID 31552026, 2019). "APOBEC mutagenesis is associated with increased expression of immune signatures, including interferon signaling, and expression of APOBEC3B is increased after stimulation of APOBEC-high bladder cancer cell lines with IFNγ." (PMID 29435122, 2018). "Treatment with phorbol ester, interleukin-1 beta, or interferon gamma increased the level of G-CSF, granulocyte-macrophage colony-stimulating factor, and macrophage colony-stimulating factor in an in vitro bladder cancer cell line study." (PMID 24885603, 2014). "We showed that FOXP3 is critical in the ability for IFNγ to activate PD-L1 in bladder cancer cells." (PMID 39099201, 2024). "And IFNG was demonstrated to inhibit the activity of bladder cancer stem cells." (PMID 35265613, 2022). "This led us to investigate whether a curated urothelial in vitro IFNγ-response gene set applied to the unsupervised clustering of bladder cancer cohorts to yield an “IFNγ-signature” score would be more informative of tumour IFNγ response." (PMID 36358715, 2022). "Furthermore, in bladder cancer patients, risk scores were inversely linked with the expression levels of immune marker genes (CD8A, CD80, etc.)and immune activation‐related genes (IL6, IFNG, etc.)." (PMID 37771276, 2023).
bladder cancer (continued). "MB49 cells have a low basal expression of FOXP3 and PD-L1, whereas stimulation of MB49 cells by IFNγ leads to upregulation of both FOXP3 and PD-L1, consistent with our findings in human bladder cancer cell lines." (PMID 39099201, 2024). "As IFNγ is a key regulator for PD-L1 expression, we tested the ability for IFNγ to induce expression of endogenous FOXP3 and PD-L1 in HT1376, T24, and SW780 bladder cancer cell lines by flow cytometry." (PMID 39099201, 2024). "In bladder cancer, we defined a novel mechanism whereby FOXP3 mediates the activation of the immune checkpoint PD-L1 by the cytokine IFNγ." (PMID 39099201, 2024). "Interferon gamma (IFNγ) is central to the inflammatory immune response, such as that entrained by BCG immunotherapy for bladder cancer." (PMID 36358715, 2022). "Immunohistochemistry staining in bladder cancer tissues further validated that strong staining of IFNG was observed near the tumour borders rather than around PD1hi CD200hi CD4+ exhausted T cells." (PMID 37313656, 2023). "When applied to the unsupervised clustering of non-muscle-invasive bladder cancers, the IFNγ-signature predicted longer recurrence-free survival." (PMID 36358715, 2022). "The role of interferon gamma (IFN-γ) expression in long-term survival has not been studied in patients with urinary bladder cancer (UBC)." (PMID 36040901, 2022). "In addition to this, transcriptome analysis of MB49, BBN-induced murine bladder cancer cell line, revealed that MB49 cells express highly immunogenic class I and class II peptides which induced strong IFNγ response in T cells stimulated by neoantigen peptide-pulsed dendritic cells." (PMID 31779626, 2019).
lung adenocarcinoma (80 papers, 2007 to 2025). A carcinoma that arises from the lung and is characterized by the presence of malignant glandular epithelial cells. "The present study examined the expression, mutation pattern, and protein-protein interaction of 24 interferon gamma response genes in lung adenocarcinoma." (PMID 33839701, 2021). "Our observations indicate a positive correlation between elevated MDH1 levels and increased immune cell infiltration, activation of CD8+ T cells, and enhanced interferon-gamma (IFN-γ) response in lung adenocarcinoma (LUAD)." (PMID 40948768, 2025). "ERS-related autophagy is also observed in lung adenocarcinoma, where interferon gamma (IFN-γ) induces ERS and UPR in lung adenocarcinoma cells by activating the JAK1/2–STAT1 and AKT–mTOR signaling pathways." (PMID 39080273, 2024). "We found that TAMs infiltrating lung adenocarcinomas contained glycogen and that a combination of GM-CSF and IFNγ triggered glycogen synthesis from lactic acid by TAMs from ovarian ascites." (PMID 39424955, 2024). "A complementary study demonstrated that MAPK signalling regulated epidermal growth factor- and interferon-gamma-induced PD-L1 expression in lung adenocarcinoma cells and that inhibition of MEK1/2 attenuated PD-L1 upregulation." (PMID 35228614, 2022). "Interferon-gamma (IFN-γ) plays a complex role in modulating tumor microenvironment during lung adenocarcinoma (LUAD) development." (PMID 33839701, 2021). "Similar to PD-L1 mRNA, PD-L1-lnc in various lung adenocarcinoma cells is significantly upregulated by IFNγ." (PMID 33849634, 2021). "We previously reported that IFNγ enhanced PD‐L1 expression in the A549 lung adenocarcinoma cell line, while EGF enhanced PD‐L1 in the PC‐9 lung adenocarcinoma cell line, but the opposite is not true." (PMID 33491334, 2021). "Concomitant with our results it was previously reported that both EGF and IFNγ induce CD274 expression in lung adenocarcinoma cells and act through the MAPK cascade, and imbalanced PD-1/PD-L1 interaction is observed during viral infections." (PMID 34045585, 2021). "GSEA revealed that low HIP1R mRNA expression was closely associated with allograft rejection, inflammatory responses, IL6-JAK-STAT3, IL2-STAT5, and interferon gamma response pathways in lung adenocarcinoma." (PMID 32403421, 2020). "Our experiments demonstrated that both EGFR and MEK1/2 inhibitors decrease EGF‐ and IFNγ‐induced PD‐L1 expression, potentially increasing immunogenicity of lung adenocarcinoma cells." (PMID 30972766, 2019). "Subsequently, we demonstrated the importance of MAPK signaling in the upregulation of PD‐L1 by growth factors and IFNγ in lung adenocarcinoma cell lines, which was mediated through CD274 mRNA stability and STAT1 activation." (PMID 30972766, 2019). "With inhibition of inhibiting the JAK/STAT3 signalling pathway by STAT3 inhibitors, we found IFNγ-JAK-STAT1 pathway activation by IFNγ could further keep lung adenocarcinoma cells from proliferation and promote its apoptosis." (PMID 36185620, 2022). "In addition, patients with lung adenocarcinoma lack antitumor innate immunity at baseline including tumor-infiltrating NK cells, which are less cytolytic due to low expression of granzyme B and interferon-gamma." (PMID 35565302, 2022). "While the genes downregulated upon MGA loss in our lung adenocarcinoma cells did not delineate evident functional pathways, the downregulated genes in the colon organoids were involved in inflammatory and interferon gamma responses." (PMID 34236315, 2021). "However, Gao et al16 observed that treatment of lung adenocarcinoma cells with IFNγ led to activation of JAK2‐STAT1 and PI3K‐AKT pathways." (PMID 30039553, 2018). "Furthermore, MEK signalling has also been shown to regulate PD-L1 expression in tumour cells specifically via epidermal growth factor- and interferon-gamma-induced PD-L1 expression in lung adenocarcinoma cells and blockade of MEK1/2 attenuated PD-L1 upregulation." (PMID 35228614, 2022).
lung adenocarcinoma (continued). "We transfected human A549 lung adenocarcinoma cells with the RNA mimetic poly(I:C), which induces a complete type I IFN cascade, or treated these cells with recombinant IFNγ, which induces type II IFN signalling." (PMID 34358560, 2021). "Similarly, another study showed that overexpression of PSAT1 promotes the metastasis of lung adenocarcinoma via the inhibition of STAT1 as well as its downstream targets, IRF1 and IFNG." (PMID 40298450, 2025). "In a representative lung adenocarcinoma cell line panel, stimulation with EGF or IFNγ increased CD274 mRNA and PD‐L1 protein and membrane levels, which were further enhanced by combining EGF and IFNγ." (PMID 30972766, 2019). "This suggests that activation of the MAPK, PI3K/mTOR and IFNγ pathways is related to increased CD274 mRNA levels in lung adenocarcinomas without targetable genetic alterations." (PMID 30972766, 2019). "Our results indicate that growth factor‐dependent MAPK signaling plays an important role in basal and IFNγ‐induced PD‐L1 expression of lung adenocarcinoma without targetable genetic alterations." (PMID 30972766, 2019). "In conclusion, MAPK pathway activity plays a key role in EGF‐ and IFNγ‐induced PD‐L1 expression in lung adenocarcinoma without targetable genetic alterations and may present a target to improve the efficacy of immunotherapy." (PMID 30972766, 2019). "Given the importance of tumor-intrinsic IFNγ signaling in sensitizing KPAR tumors to antitumor immune responses, the ability of oncogenic KRAS to suppress IFN pathway signaling may represent a major mechanism of immune evasion in KRAS-mutant lung adenocarcinoma." (PMID 38635884, 2024).
helminth infection (78 papers, 2005 to 2025). "Vitamin A deficiency is known to trigger a strong Th1-regulated IFNγ response, along with the downregulation of the Th2-response, which further predisposes individuals to protozoa and helminth infections." (PMID 37111135, 2023). "Typically, chronic helminth infections are associated with the induction of a biased Th2associated immune response, although the response to schistosome parasites prior toegg-laying is thought to comprise a mixed Th1/Th2 phenotype with IFNγ productionalongside IL-4 and IL-5." (PMID 21445234, 2011). "Research has shown that helminth infection elevates intestinal levels of interferon-gamma (IFN-γ), which activates EGCs and stimulates the secretion of CXCL10." (PMID 41305570, 2025). "Helminth infections can modulate immune responses, potentially impacting the performance of interferon-gamma release assays (IGRAs) such as the QuantiFERON-TB Gold Plus (QFT-Plus)." (PMID 39435458, 2024). "It is noteworthy that maternal helminth infection during pregnancy negatively affected the frequency of IFNγ-producing T cells in cord blood of neonates and the development of Th1 immunity in BCG-vaccinated offspring." (PMID 36753434, 2023). "Disruption of the IFNγ–EGC signalling axis during helminth infection in mice enhances the inflammatory response and impairs tissue healing." (PMID 35533467, 2022). "In vivo blockade of IL-10 signalling during helminth infection resulted in an expansion of IFNγ+ and Tbet+ Th1 cells in the small intestine and a coincident decrease in IL-13, IL-5 and GATA3 expression by intestinal T cells." (PMID 35428872, 2022). "Others have suggested that helminth infection negatively influences the magnitude of the QFT IFNγ response, resulting in a higher likelihood of an indeterminate result." (PMID 30013573, 2018). "By contrast, helminth infections typically direct the immune system toward a type 2 response, characterized by high levels of the cytokines IL-4 and IL-10, which can antagonize IFNγ production and its biological effects." (PMID 29312343, 2017). "Although helminth-specific IgE, IL-5 and IFNγ responses were all decreased in fexofenadine treated mice, eosinophil numbers at the site of worm infection were significantly elevated." (PMID 26204515, 2015). "The type of immune response is not fixed in time and may swiftly convert in the initial stages of infection, such as the switch from IFNγ to IL-4 production during helminth infection and IL-17 to IFNγ production during bacterial and fungal infections." (PMID 34608235, 2022). "In our effort to understand how IL-17A might be required for full type-2 immunity, we have discovered that IL-17A suppresses early IFNγ expression in the lung during helminth infection." (PMID 32636457, 2020). "Helminth infections can promote the secretion of IL-10 by regulatory T cells, and this can downregulate the expression of pro-inflammatory cytokines such as IL-12p70 and IFNγ." (PMID 30467504, 2018). "may contribute to the chronicity of helminth infection by reducing anti-helminth Th2 cells and converting them into IFNγ-secreting cells." (PMID 26147567, 2015). "Furthermore, a small body of work suggests that helminth infections may influence interpretation of interferon-gamma (IFN-γ) release assays (IGRAs) used to diagnose LTBI, which rely on Th1-mediated immune responses." (PMID 30619265, 2018). "However, the possibility has been raised that helminth infection during pregnancy may reduce the IFNγ response to PPD, which we cannot eliminate as we did not screen the mothers for intestinal infections." (PMID 22243970, 2012). "Whereas a study assume that Schistosoma proteins may reduce inflammatory process associated with HTLV-1 infection through interferon-gamma level decrease, another one report that treatment of helminthic infection does not affect the risk of HAM/TSP development." (PMID 29554087, 2018).
helminth infection (continued). "Helminth infection did not alter the production of IL-17, IFNγ, or IL-10 by antigen-specific CD4+ T cells in the draining lymph nodes, as determined by re-stimulation of a defined number of cells with recombinant H1." (PMID 36753434, 2023). "STAT1 is one of the most important players in the IFNγ signaling important for the classic activation of macrophages, which is typical in bacterial infections but not in helminth infections." (PMID 30783117, 2019). "After helminthic infection, IgE production is regulated by both IL4 and IFNγ." (PMID 25415191, 2014). "During helminth infection and in response to increased levels of IFNγ, EGCs upregulate C-X-C motif chemokine ligand 10 (CXCL10) to recruit IFNγ+CD8+ T cells to the tunica muscularis in order to amplify the IFNγ tissue response and propagate immune cell activation." (PMID 35533467, 2022). "Finally, although CD4+ TRM cells can produce IFNγ/IL-17, and IL-4/IL-13 following helminth infection, their production of IL-10 has not previously been reported." (PMID 25974019, 2015).